IDH1 (isocitrate dehydrogenase (NADP(+)) 1)
Diseases named in the same sentence as IDH1 in open-access papers (continued):
Sharing a sentence is not in itself a finding about the gene and the disease.
tumor (continued). "The patient underwent urgent tumor resection that revealed a GBM harboring an isocitrate dehydrogenase 1 mutation (IDH1)." (PMID 30567605, 2018). "The detection of IDH1 R123H mutation in the tumor tissue represented a significant positive prognostic factor for both PFS and OS of GBM patients." (PMID 29662659, 2018). "IDH1 appears to function as a tumor suppressor that, when mutationally inactivated, contributes to tumorigenesis in part through the induction of the HIF-1 pathway." (PMID 29953478, 2018). "Accordingly, the increase in the TRAF4 level was positively associated with the wild-type IDH1/2 gene, older age, advanced tumor grade, and higher Ki-67 LI (P < 0.0001)." (PMID 30348972, 2018). "We found that a quantity of IDH1-mutant protein expressed in tumors was positively associated with RFS, but not with OS in all tested patients, suggesting that certain factors can transiently control tumor growth as a result of the IDH1 mutation." (PMID 29643764, 2018). "Consistent with our observed association, we found that patients with IDH1 p.R132H mutated tumours in our cohort were generally younger than patients with IDH1 p.R132H wild-type tumours." (PMID 30412573, 2018). "To further study the effects of IDH1 mutations in tumor development, we have generated transgenic zebrafish that express IDH1 mutants under the control of various CNS-specific promoters." (PMID 29953513, 2018). "In particular, the IDH1/2 mutation and its metabolic changes pinpointed the strong coherence between metabolic and genetic alterations and highlighted the relevance of tumor-metabolism in glioblastoma multiforme." (PMID 28380457, 2017). "In IDH1-mutated tumor samples Mcl-1 expression was significantly decreased, suggesting a broad biological applicability of this observation." (PMID 29057925, 2017). "Mutations in IDH1/2 within LGGs are highly prevalent, and can be observed at a rate of 70–80% in all tumours within this subgroup." (PMID 28629182, 2017). "The epigenetic dysregulation imparted by such IDH1 mutations can be clearly observed by the global hypermethylation phenotypes observed in tumor types bearing these alterations." (PMID 29062039, 2017). "Among genetic and chromosomal alterations, IDH1 mutation and 1p/19q-codeletion were prevalent in almost all tumor cells and are considered to be the trunk alterations." (PMID 28270234, 2017). "We observed one H3/IDH1 wildtype primary tumor (HGG11) with an increased number of somatic mutations compared to other primary tumors, and was identified to harbor a germline MLH1 splice missense mutation." (PMID 29084603, 2017). "How IDH1 and 2 neomorphic alleles are common in specific tumor types and the possible mechanism behind that will be discussed, as well." (PMID 28785398, 2017). "One of these two tumours harbored an IDH1 R132 mutation, whereas the other tumour was confirmed to be wildtype for IDH." (PMID 28484589, 2017). "Age, KPS, tumor resection degree, tumor size, Ki-67 index, tumor grade, 1q/19p co-polysomy, 1q/19p single polysomy, and IDH1/2 mutation were included in Cox regression analysis." (PMID 28978019, 2017). "Those whose tumor was positive for IDH1 mutation had marginally significantly higher median 5-mC% levels than those whose tumor was negative for IDH1 mutation (P=0.078)." (PMID 28968983, 2017). "Significant differences in SWI-LIV values were found dependent on the WHO tumour grade, IDH1-R132H mutational status and type of MRI contrast-enhancement." (PMID 27300198, 2017).
tumor (continued). "H3K27M/G34V and IDH1 mutations were as expected clonal and conserved across primary and recurrent tumor pairs." (PMID 29084603, 2017). "In primary tumours, 21 (21/47, 44.68%) IDH1 mutations were detected, all of which were the R132H mutation (CGT-CAT)." (PMID 29026176, 2017). "Next, we used MRK-A to examine the anti-tumor properties associated with in vitro 2-HG inhibition in patient-derived mutant IDH1 cell lines." (PMID 29062039, 2017). "That, as will also be discussed later in this article, explains the mutual exclusivity seen in neomorphic IDH1 and 2 alleles where one tumor cell cannot have both IDH1 and 2 neomorphic alleles." (PMID 28785398, 2017). "This provides therapeutic opportunities to exploit the metabolic vulnerabilities specific to IDH1 mutated tumor." (PMID 28052098, 2017). "Three patients had a tumour with the R132H mutation in the IDH1 gene, with 11 patients having wild type IDH1 GBM." (PMID 29156557, 2017). "More and more, molecular markers such as the IDH1 mutational status are increasingly incorporated in clinical decision making in addition to the tumour grade." (PMID 27300198, 2017). "The tumor-associated IDH1/2 mutations gain the ability to generate (R)-2-hydroxyglutarate ((R)-2-HG)." (PMID 27557497, 2016). "The combination of 1p19q deletion and TERT and IDH1 mutational status separated tumor groups that showed distinct age of diagnosis and outcome." (PMID 27172220, 2016). "In the tumor sample, we identified a recurrent somatic IDH1-mutation affecting Arg132, while in normal liver tissue and peripheral blood, no variants were detected, as expected." (PMID 26920730, 2016). "For the present study, we excluded one tumor with immunoreactivity for the mutated IDH1 protein (mIDH1R132), leaving a total number of 174 tumors." (PMID 27626492, 2016). "Next, we performed multivariate Cox regression analysis incorporating KIF23 expression, age, IDH1 mutation and tumor grade." (PMID 27013586, 2016). "To this end, we performed survival analysis utilizing a multivariate Cox proportional hazard model that included IDH1/2 mutational state, age, sex, tumor grade, and lncRNA expression as independent variables in the survival model." (PMID 27923049, 2016). "The presence in the tumor of a mutation of the IDH1 or, less commonly, IDH2 genes similarly is associated with better response to therapy and longer survival." (PMID 27242937, 2016). "Patients with adequate tumor specimens were analyzed for genetic changes including isocitrate dehydrogenase 1 (IDH1) mutations, 1p/19q loss of heterozygosity (LOH) and promoter methylation of O6-methylguanine-DNA methyltransferase (MGMT)." (PMID 27590514, 2016). "It is well established that an aberrant hypermethylation of tumor DNA can be caused by mutations in epigenetic modifiers such as IDH1, IDH2, TET1, TET2, and SDH-subunits." (PMID 26848979, 2016). "The majority of TET gene mutations occur in hematologic malignancies, whereas IDH1/2 mutations are predominantly detected in tumors of the central nervous system." (PMID 27050164, 2016). "All 758 tumor samples from Cohort 1 were screened for mutations in IDH1/2 and TERT hotspots and the copy number status of 1p/19q." (PMID 27503138, 2016). "In IDH1 mutant patients, smaller residual tumor volumes were associated with increased TTR (HR 1.01, p = 0.03)." (PMID 27344556, 2016). "IDH1 was thought to be an oncogene whose mutations have stimulated the burgeoning field of tumor metabolism." (PMID 27469031, 2016). "In patient 3, double staining with anti-ATRX and anti-IDH1 R132H antibodies identified: (i) areas with maintained ATRX expression in tumor cells, and (ii) areas with diffuse loss of ATRX expression in tumors cells." (PMID 27036230, 2016). "This new function generates >100-fold elevated concentrations of D2HG in tumor cells bearing an IDH1 or IDH2 mutation, while there is only trace amount of D2HG in normal cells." (PMID 27316347, 2016).
tumor (continued). "The presence of both IDH1-mutated and IDH1-wild type individuals introduces considerable variability into the dataset, since these two tumor types appear to represent divergent biological origins." (PMID 27898674, 2016). "Immunoblot analysis confirmed that the IDH1-mutant GBMs had significantly reduced total tissue HIF1α protein suggesting a profound dysregulation of the hypoxic response in xenograft tumours expressing the R132H IDH1 mutation." (PMID 27820599, 2016). "High frequency of the IDH1 mutation and LOH1p/19q in ODs suggests critical roles in early tumor development." (PMID 26468983, 2015). "We applied annotated tissue microarrays (TMAs) to evaluate the correlation between the expression of CD151 or α3β1 integrin and clinicopathological parameters, including tumor grade, IDH1 mutation status, and patient survival." (PMID 26377974, 2015). "Tumour metabolites have also been shown to correlate with tumour-specific genetic mutations, for example, IDH1 mutation in glioma, SDH and VHL mutations in paraganglioma and MYCN amplification in neuroblastoma." (PMID 26348444, 2015). "Magnetic resonance imaging was performed and immunohistochemistry was used to identify tumours with the IDH1-R132H mutation." (PMID 25849605, 2015). "Up to half will harbour a mutation in IDH1 which suggests that they arose from a previously undiagnosed low-grade tumour." (PMID 25849605, 2015). "Our TMA-based analyses reveal significant correlation between CD151 or its associated α3β1 integrin and tumor grade, patient survival, and IDH1 gene status." (PMID 26377974, 2015). "More specifically, they can be classified into lncRNA signature subgroups: (i) astrocytic tumor with high EGFR amplification; (ii) neuronal-type tumor; and (iii) oligodendrocytic tumor enriched with IDH1 mutation and 1p19q co-deletion." (PMID 26230711, 2015). "If a tumour at presentation was found to be wild-type (WT) for IDH1 R132 mutations, the relapse samples were also WT (19/37 patients)." (PMID 25432631, 2015). "EGFR amplification was exclusively found in tumors with wild-type IDH1/2 (p < 0.0001) and showed co-occurring association with TERTp mutation in IDH1/2 wild-type tumor subset (p = 0.002)." (PMID 26369702, 2015). "To verify the potential effects of IDH1 mutation on tumor progression, we over-expressed IDH1-R132H in GL261 cells creating mIDH1-GL261." (PMID 25849072, 2015). "One hundred and two tumour samples from 37 patients were analysed for IDH1 R132 of which 48 (49 %) were found to harbour a R132 IDH1 mutation." (PMID 25432631, 2015). "Among the 5 patients with an IDH1/2 mutated tumor, there were 4 with either radiographic response or SD ≥6 cycles." (PMID 25529192, 2015). "Among patients with IDH1-R132H positive tumours, age ≥ 50 years and volume of CE tumour ≥ 5 cm3 were associated with death within 12 months." (PMID 25849605, 2015). "To further investigate this possibility, we evaluated the remaining tumor tissue for IDH1/2 mutation." (PMID 25529192, 2015). "We also show that loss of p16/CDKN2A is found in both IDH1 WT and mutant cartilaginous central tumours, indicating that the two genetic events are unrelated." (PMID 25432631, 2015). "As this is a retrospective study that included patients treated over a long time period, limitations of the study include the lack of O6-methylguanine–DNA methyltransferase (MGMT) methylation status and IDH-1 mutation status for only a portion of tumours." (PMID 26015297, 2015).
tumor (continued). "In 2009, it was demonstrated by the team at Agios that mutations in IDH1 are associated with high levels of 2-HG in the tumor." (PMID 24581008, 2014). "Frequent recurrent mutations in IDH1 were initially discovered in GBM (12%) following whole-exome sequencing of 22 patient tumor samples." (PMID 24622842, 2014). "In tumours that have these mutations in IDH1 or IDH2, it accumulates to millimolar levels, high enough to detect by a technique called MR spectroscopy, similar to MRI." (PMID 24581008, 2014). "This was also verified in patient samples, with a strong correlation between the amount of 2-HG in tumor tissue and IDH1/2 mutation status." (PMID 24622842, 2014). "The patient with homozygous IDH1 mutation was 53 years old and had OS of 34.6 months; the tumour was a primary GBM and surgery was followed by both chemo- and radiotherapy." (PMID 24868540, 2014). "To investigate the association between ATRX mRNA expression alteration and IDH1/2 mutations, we screened tumor samples in our cohort for IDH1/2 mutations using pyrosequencing." (PMID 24810474, 2014). "The TERT promoter/IDH1/2 mutational profiles of each tumor type can be used in several aspects of the clinical process including stratification of patients, examination of therapeutic response, and selection of treatment, among others." (PMID 24722048, 2014). "A new model has been proposed in which the phenotypic features which distinguish IDH1 mutant tumours are those associated with lower grade lesions, supporting their development as part of a progression pathway regardless of clinical presentation." (PMID 23451042, 2013). "We identify specific subtypes of tumour and vascular biology which are closely linked with IDH1 mutation in young adults." (PMID 23451042, 2013). "Previous studies demonstrated that the decrease level of 5 hmC in tumors was due to the reduced expression of TET1/2/3 and IDH2 genes or tumor derived IDH1 and IDH2 mutations." (PMID 23671639, 2013). "Based on our findings we propose that tumor cells that carry the IDH1 mutation undergo a metabolic switch involving increased mitochondrial activity leading to impaired proliferation and a relatively good prognosis." (PMID 24252742, 2013). "The aberrant gene expression profile activated by mutant IDH1 confers a block to differentiation causing the malignant expansion of tumor-initiating cells with capacity to self-renew." (PMID 24077826, 2013). "Whilst oligodendroglial differentiation had been noted in IDH1 mutant tumours previously, the observation of a significant association with neoplastic small cells is novel." (PMID 23451042, 2013). "The elevated 2-HG levels, which are characteristic of IDH1 and IDH2 mutated tumours, is also potentially useful as a biomarker to identify IDH1/IDH2 mutational status or monitor tumour growth or treatment efficacy in a non-invasive way." (PMID 22771539, 2013). "An additional study has investigated the relationship between tumor enhancement, edema, IDH1 mutational status, MGMT promoter methylation, and survival in GBM." (PMID 24202336, 2013). "Direct sequencing of IDH1 exon 4 demonstrated that the grade III tumor bore a heterozygous G395A (R132H) mutation, validated by immunohistochemistry." (PMID 24077805, 2013). "When such tumours arise as solitary lesions in the medullary cavity (central CS) or more rarely in the periosteum, ~50% harbour either a somatic IDH1 (isocitrate dehydrogenase 1) or IDH2 heterozygous mutation." (PMID 23863747, 2013).
tumor (continued). "IDH1- mutations or other molecular events with similar properties mark tumor initiation and provide a microenvironment with increased chromosomal and genetic instability allowing additional alterations to occur." (PMID 22844452, 2012). "GBM that have mutations in IDH1 or IDH2 are reported to undergo metabolic remodeling that influences the tumor survival program in response to treatment and hypoxia." (PMID 23047041, 2012). "While necessary for tumor initiation the importance of mutated IDH1 for tumor maintenance remains to be elucidated." (PMID 22844452, 2012). "The IDH1- mutational status remained unchanged in all but one tumor pair (86%) represented by 14 tumors in total (87%)." (PMID 22844452, 2012). "In all, 7 out of 11 DNA samples isolated from frozen tumour tissues showed IDH1 mutations in the sequencing analysis." (PMID 21326241, 2011). "In one study, tumor tissue from glioblastomas with IDH1 R132 mutations had 38% lower NADP+-IDH activity on average than tissue from glioblastomas without IDH mutations." (PMID 21326614, 2011). "In general, most cells stained positively for mIDH1R132 in tumours that harboured the mutated IDH1 R132H protein." (PMID 21559010, 2011). "Only in one case, tumour cells presenting LOH were observed after disappearance of cells presenting IDH1 mutation." (PMID 21326241, 2011). "This approach was based on the knowledge that genes with evident DNE, such as EGFR and IDH1, represent nearly 100% of single heterozygous mutations in tumour specimens and cell lines." (PMID 21668955, 2011). "The mutated template was no longer detectable in adherent cells grown in vitro (in four cases after the first passage and in six cases after the second passage) derived from the tumour samples with IDH1 mutations." (PMID 21326241, 2011). "Although we did not define that beyond any doubt, the cells that survived after the elimination of tumour cells with IDH1 mutation are most likely normal cells." (PMID 21326241, 2011). "Lower tumour grade, extent of resection, younger age, good performance status, mutation of IDH1, as well as an intact neurological function are recognised as favourable prognostic factors for HGG." (PMID 20953324, 2010). "Additionally, an evaluation of the tumor mutation burden (TMB) showed that the IDH1 mutation was among the top 20 most frequent mutations in low-score GBMs, which correlated with better survival for patients with a low-risk score." (PMID 40565338, 2025). "More mutations in CSF than tumor; IDH1/H3F3A concordant; WES feasible in CSF ctDNA." (PMID 41458584, 2025). "Moreover, ICC exhibits unique mutation enrichments, such as IDH1/2 mutation, NTRK gene fusions, FGFR2 fusions/rearrangements, and RET fusions, particularly IDH1 mutations, which have higher mutation frequencies than other tumor types." (PMID 41236411, 2025). "Similarly, a mutation in IDH1, found in specific glioblastoma subtypes, is being explored in clinical trials of peptide vaccines to prevent tumor progression, thereby eliciting mutation-specific T-cell responses." (PMID 40746549, 2025). "It is interesting to note how IDH1 (R132H) mutations and PD-L1 expression interact, pointing to a complicated relationship that could affect immune regulation and the tumor microenvironment (TME)." (PMID 39906459, 2025). "Although a post hoc analysis controlling for age yielded robust results, it is important to consider other factors such as tumor location and volume, grade, IDH1 mutation, edema, and the use of antiepileptic drugs, which may influence cognitive outcomes." (PMID 40612713, 2025). "The 2-HG concentration in patient-derived IDH1-mutated tumor cells ranged from 5 to 35 mM." (PMID 40564198, 2025). "The extent of downregulation across PARPi-treated tumor populations provided early evidence for the importance of loss of end protection in the IDH1-mutant context and further supports the notion that the PARPi sensitivity in IDH-mutant cancers is a consequence of a defect in HDR." (PMID 41357766, 2025).